MAPT (microtubule associated protein tau)
Diseases named in the same sentence as MAPT in open-access papers (continued):
Sharing a sentence is not in itself a finding about the gene and the disease.
tauopathies (continued). "Additionally, MAPT missense mutations directly contribute to tauopathies, such as the V337M mutation that is associated with frontotemporal dementia (FTD)." (PMID 40858609, 2025). "Further work is required to confirm if this mechanism is universal across other MAPT mutations and tauopathies and to dissect whether the effects of tau on the nucleolus are direct or secondary to broader transcriptomic dysregulation." (PMID 41255983, 2025). "In addition to the autosomal dominant mutations, MAPT variants also serve as a risk factor for primary tauopathies." (PMID 38528629, 2024). "Over 80 mutations of the MAPT gene have been discovered to be associated with tauopathies." (PMID 39107835, 2024). "In familial tauopathies, specific mutations in the MAPT gene are known to trigger tau aggregation." (PMID 38994964, 2024). "FTD is one of the tauopathies linked to the MAPT gene, which encodes tau protein." (PMID 38607741, 2024). "Tauopathies are a group of age-related neurodegenerative disorders caused by pathological hyperphosphorylation and aggregation of the microtubule-binding protein tau (encoded by MAPT)." (PMID 38469687, 2024). "Additionally, we included data from patients with a definite tauopathy, based on pathology or the presence of a known pathogenic MAPT mutation." (PMID 39200244, 2024). "Tauopathies show the aggregation of abnormal tau, also called microtubule-associated protein tau." (PMID 39457570, 2024). "In tauopathies, the microtubule-associated protein tau is hyperphosphorylated and aggregated." (PMID 38396035, 2024). "PS19 mouse line overexpresses MAPT with the P301S mutation and is a representative Tauopathy model." (PMID 38488468, 2024). "In addition, certain MAPT mutations are reported to be rare causes of primary tauopathies considered as atypical parkinsonism syndromes (e.g. PSP and CBD)." (PMID 38554150, 2024). "This study contributes to the understanding of metabolic abnormalities in tauopathy, by demonstrating that the MAPT-N279K mutation increases the abundance of oxidised phospholipids, with tunicamycin-induced ER stress appearing to reverse this effect in MAPT mutant neurons." (PMID 38790613, 2024). "Because abnormally phosphorylated tau (pTau) is a hallmark of AD and primary tauopathies, we investigated whether the transgene product, MAPT*P301S protein, undergoes post-translational modification in the Tg12099(+/+) rats." (PMID 39160375, 2024). "Tauopathies comprise a number of adult-onset neurodegenerative diseases characterized by intracellular aggregation and transcellular propagation of abnormal forms of the microtubule-associated protein tau (MAPT), commonly known as tau protein." (PMID 37087820, 2023). "Leveraging isogenic iPSC lines to understand the contribution of a single allele to downstream phenotypes is a powerful system that, when applied here, has revealed lncRNAs shared across MAPT mutations that also change with tau accumulation in mouse models of tauopathy." (PMID 37730840, 2023). "Therefore, we conclude that the MAPT IVS9-7 A > T variant found in our case is a novel mutation that causes predominant 4 repeat tauopathy clinically presenting with rtvFTD." (PMID 37563653, 2023). "Mutations in microtubule-associated protein tau can cause altered ratios of 3- or 4-repeat isoforms of tau protein or changes in the structure of tau, both of which can cause tau to aggregate and cause a range of rare inherited tauopathies." (PMID 37556474, 2023). "Therefore, we conclude that the MAPT IVS9-7A > T variant is causative for 4 repeat tauopathy and clinically presents as rtvFTD." (PMID 37563653, 2023). "Interestingly, dysfunction in CBF regulation was recently observed in mice expressing MAPT P301S or P301L mutations, even before tauopathy and neurodegeneration." (PMID 36707904, 2023). "Familial tauopathies are caused by mutations in the MAPT gene and are often autosomal dominant." (PMID 37013265, 2023).
tauopathies (continued). "Tauopathies are a complex collection of clinical syndromes characterized by the deposition of misfolded tau proteins (tubulin-associated unit, also called microtubule-associated protein tau (MAPT) protein), chiefly in neurons but also in glial cells and the extracellular space." (PMID 37238166, 2023). "To explore the contribution of lncRNAs to tauopathy, we examined whether there were a common set of lncRNAs that are downstream of MAPT mutations." (PMID 37730840, 2023). "Indeed, to investigate the molecular processes of tau pathology, iPSCs have been generated from individuals carrying different MAPT mutations and subsequently differentiated into mainly cortical neurons, which are known to be affected in tauopathies." (PMID 37408218, 2023). "More than 50 pathogenic mutations in MAPT have been reported and linked to tauopathies." (PMID 35517047, 2022). "MAPT mutations of different subtypes have been linked to various tauopathies." (PMID 36051222, 2022). "This approach was chosen on the grounds that alterations in 3R:4R isoform ratios are centrally involved in the neurodegenerative process, associated with specific MAPT variants as well as classes of sporadic tauopathies, and are relevant for postmortem diagnostics of tauopathies." (PMID 36066634, 2022). "Although the majority of tauopathies are sporadic, more than 50 mutations in the exons and introns of the MAPT gene have been reported to be linked to the onset of tauopathies, and these cases are referred to as frontotemporal dementia and parkinsonism linked to chromosome 17 (FTDP-17T)." (PMID 35513543, 2022). "Tauopathies can be sporadic or inherited when caused by mutations in the MAPT gene encoding the microtubule-associated protein tau, but the molecular mechanisms leading to neuronal toxicity and death, and therefore potential therapeutic targets, are still not fully understood." (PMID 35317195, 2022). "Tauopathy encompasses clinically heterogeneous neurodegenerative disorders, such as Alzheimer’s disease and frontotemporal lobar degeneration, characterized by the brain deposition of the microtubule-associated protein tau, observed as NFTs." (PMID 35216455, 2022). "The majority of tauopathies, defined by intracellular accumulation of hyperphosphorylated Tau (pTau) proteins, are “sporadic,” and a minority are inherited, caused by mutations of the microtubule-associated protein Tau (MAPT) gene." (PMID 36384116, 2022). "Tauopathies refer to a group of neurodegenerative diseases with intracellular accumulation of hyperphosphorylated and aggregated microtubule-associated protein tau (MAPT) in neurons and glial cells." (PMID 34575885, 2021). "In addition, mutated forms of tau protein aggregate in inherited tauopathies are associated with MAPT mutations that lead to a change in the primary structure of tau." (PMID 34389969, 2021). "Given that FTLD-MAPT is a pure tauopathy with underlying genetic mutations in MAPT, the robust astrocyte phenotype and pathological accumulation of tau in astrocytes might suggest additional mechanisms are contributing to disease pathogenesis." (PMID 34172091, 2021). "On the contrary, FTDP-17 are primary tauopathies with different mutations in the MAPT gene." (PMID 33924882, 2021). "Moreover, the loss of Cx3cr1 causes further increase in microglial activation and MAPT phosphorylation in tauopathy mice." (PMID 34899188, 2021). "In accordance with that, mutations altering alternative splicing of exon 10 of MAPT cause some tauopathies, including FTDP-17, and may be associated with others such as Huntington’s disease, whose patients display a four-repeat tauopathy with nuclear rods." (PMID 33934221, 2021). "Unbound microtubule-associated protein tau (MAPT) exists physiologically as a soluble unstructured protein, but under pathogenic conditions tau assembles into insoluble β sheet-rich amyloidogenic fibrillar inclusions in AD and other tauopathies." (PMID 33496840, 2021).
tauopathies (continued). "Tauopathies are a large group of neurodegenerative diseases, unified by accumulation in the brain of fibrillar aggregates of the protein microtubule-associated protein tau (MAPT)." (PMID 33830330, 2021). "Tauopathies are a group of neurodegenerative diseases characterized by the progressive accumulation across the brain of hyperphosphorylated aggregates of the microtubule-associated protein tau that vary in isoform composition, structural conformation and localization." (PMID 33071951, 2020). "While rare mutations in the MAPT gene underlie familial forms of disease (e.g., frontotemporal dementia with parkinsonism-17), the majority of tauopathies are sporadic and of unknown origin." (PMID 33117266, 2020). "Subtypes of MAPT mutations were associated with different types of tauopathies." (PMID 32184751, 2020). "Tauopathies, particularly those with MAPT mutations, had the smallest volumes." (PMID 32143137, 2020). "Their proposal is supported by the reanalysis of neuropathology data for a cohort of MAPT mutation cases that concluded each case could be readily classified into one of the sporadic primary tauopathy subtypes." (PMID 33121065, 2020). "Both exonic and intronic mutations in the MAPT gene have been identified in primary tauopathies." (PMID 32677986, 2020). "Mutations in human APP, the presenilins or MAPT known to cause familial AD and tauopathies, respectively, or a combination of these can easily be delivered to BSCs from transgenic or non-transgenic mice in order for us to understand mechanisms related to AD and develop novel BSC models." (PMID 31791377, 2019). "Small molecule therapies and tau monoclonal antibodies are also being developed for tauopathies (with a potential for use in MAPT mutations), and other options for GRN mutations include modification of proteins such as sortilin and HDAC that lead to increased GRN levels." (PMID 31119452, 2019). "Pathological aggregation of the microtubule-associated protein tau and the preponderance of NFTs or other inclusions containing tau are defining histopathological features of AD and many neurodegenerative diseases collectively known as tauopathies." (PMID 31847365, 2019). "Tauopathies are a family of neurodegenerative disorders characterized by intra-neuronal fibrillary aggregates containing abnormally hyperphosphorylated isoforms of the microtubule-associated protein Tau." (PMID 31787873, 2019). "Moreover, single nucleotide polymorphism (SNP) at MAPT has been associated with tauopathies in development of neurodegenerative disease like Alzheimer’s and Parkinsonism." (PMID 31805998, 2019). "It has been described that the MAPT H1 haplotype—that is the most abundant—could be a genetic risk factor for some Tauopathies like PSP or CBD." (PMID 32009905, 2019). "MAPT gene mutations are identified in a number of tauopathies." (PMID 30619849, 2018). "Tauopathies are a group of neurodegenerative diseases predominantly identifiable by inclusions composed of aggregated, highly phosphorylated and cleaved microtubule (MT)-associated protein tau (MAPT)." (PMID 29608591, 2018). "The research linking MAPT mutations to the development of tauopathies has led to the generation of animal models over-expressing tau mutations which develop phenotypes and biochemical changes associated with tauopathies." (PMID 30174587, 2018). "We hypothesized that the mechanisms of tau deposition are different in sporadic tauopathies than when a mutation of MAPT gene is present." (PMID 30497516, 2018). "Patients who suffer from tauopathies rarely bearing mutated MAPT gene." (PMID 29991349, 2018). "This preliminary study of a Croatian cohort investigated whether certain variants of MAPT gene were associated with AD pathology as it was shown that polymorphisms in the MAPT gene increase the risk of tauopathies." (PMID 30329219, 2018). "Most of them are sporadic but certain tauopathies rely on tau gene (MAPT) mutations." (PMID 30497516, 2018).
tauopathies (continued). "The genetic imbalance associated with these MAPT mutations in FTLD raises the question of whether isoform dysregulation may also underlie sporadic tauopathies such as AD." (PMID 29273078, 2017). "Tauopathies are a diverse group of diseases featuring progressive dying-back neurodegeneration of specific neuronal populations in association with accumulation of abnormal forms of the microtubule-associated protein tau." (PMID 29089864, 2017). "In particular, in this study, we observe gender-specific differences in the age-dependent decrease of brain gene expression levels for the microtubule-associated protein tau (MAPT), a protein playing a central role in neurodegenerative diseases referred to as tauopathies." (PMID 27878758, 2017). "Collectively, these findings indicate that a versatile model of tauopathy to explore the impact of different genetic MAPT coding variants, elucidate the role of tau in neurodegeneration and evaluate genetic modifiers of disease would greatly benefit the study of a wide range of conditions." (PMID 26276810, 2015). "Therefore, the identification of a human neuronal system in which to investigate the effects of MAPT mutations and to test compounds for the treatment of tauopathies is desirable." (PMID 26220942, 2015). "The tauopathies are a class of neurodegenerative disorders characterized by hyperphosphorylation and aggregation of the microtubule-associated protein tau (MAPT) into paired helical filaments (PHFs) or straight filaments (SFs), forming neurofibrillary tangles (NFTs) in brain." (PMID 26576216, 2015). "Different microtubule-associated protein tau (MAPT) gene mutations have been identified in many different tauopathies including AD, frontotemporal dementia and Parkinsonism linked to chromosome 17 (FTDP-17), progressive supranuclear palsy (PSP) and corticobasal degeneration (CBD)." (PMID 24948216, 2014). "In addition to investigations of MAPT variants with risk for tauopathies, some studies also assessed their role in gene expression." (PMID 25324900, 2014). "Tauopathies are a group of nearly 30 neurodegenerative diseases that are characterized by intraneuronal protein aggregates of the microtubule-associated protein Tau (MAPT) in patient brains." (PMID 24409116, 2014). "The microtubule associated protein tau causes primary and secondary tauopathies by unknown molecular mechanisms." (PMID 24376810, 2013). "Similarly, tauopathies are a class of neurodegenerative diseases that are associated with the aberrant accumulations of tau proteins (MAPT) in the brain." (PMID 24688734, 2013). "From the Mendelian genes, MAPT appears to also harbor a genetic risk to develop tauopathies." (PMID 22890575, 2012). "One pathological hallmark of tauopathies is aggregation of the microtubule-associated protein tau." (PMID 22988541, 2012). "The microtubule-associated protein tau that is normally enriched in the axon becomes hyperphosphorylated and accumulates in the somato-dendritic compartment in several neurodegenerative diseases named tauopathies that are characterized by dementia." (PMID 22615831, 2012). "The affected brain accumulates many types of abnormal intracellular deposits (synuclein, β-amyloid, TDP-43), but it is dominated by deposits of microtubule-associated protein tau (MAPT), and therefore fits into the molecular neuropathological class of tauopathies." (PMID 22073019, 2011). "Interestingly, both intronic and exonic mutations in the MAPT gene encoding protein tau, are dominantly associated with various tauopathies implying that neurotoxicity results from mutant tau protein, but as well from wild-type tau by isoform imbalances." (PMID 19794916, 2009). "The ratio of p-tau217/t-tau217 to Aβ 42/40 in CSF demonstrated efficacy as a composite biomarker to identify tau lesions in carriers of the MAPT R406W mutation, and could effectively distinguish them from cognitively normal individuals and those with other tauopathies." (PMID 40901664, 2025).
tauopathies (continued). "Moreover, MAPT pathogenic variants may trigger alterations in GABAergic signaling and synaptic function, leading to pathogenesis of tauopathies." (PMID 39920674, 2025). "Studies have shown that the tauopathy-related MAPT variants and the synucleinopathy-associated SNCA mutation may make neurons more vulnerable to cellular dysfunction such as mitochondrial deficits, setting similar mechanistic paths towards neurodegenerative cell death." (PMID 38528629, 2024). "Thus, we next sought to determine the extent to which the gene signatures we observe in iPSC-neurons from MAPT mutations are relevant to gene expression changes occurring in human brains with tauopathy and the extent to which these gene signatures are occurring across neurodegenerative diseases." (PMID 36845551, 2023). "In addition, given the complex temporal trajectories of brain myeloid responses in tauopathy, future research on large cohorts of presymptomatic MAPT pathogenic variant carriers will be needed to determine which peripheral changes observed here occur prior to disease onset." (PMID 37464408, 2023). "However, tauopathies caused by mutations in the MAPT gene are frequently associated with a clinical phenotype of bvFTD or parkinsonism, although some patients may develop semantic impairment as the disease progresses." (PMID 36707904, 2023). "Although much effort has gone into characterizing the natural history and longitudinal declines of MAPT pathogenic variant carriers, we understand relatively little about the molecular mechanisms that impart risk for sporadic forms of tauopathy—whether primary or secondary." (PMID 37464408, 2023). "The MAPT gene (microtubule associated protein tau, 17q21.31) encodes tau, a protein which confers and maintains neuronal microtubule stability, and whose aberrant deposition in neuronal or glial cells results in neurodegenerative disorders known as tauopathies." (PMID 36765380, 2023). "However, the underlying mechanism of how MAPT mis-splicing triggers tauopathy remains elusive." (PMID 35216455, 2022). "A shift of alanine to threonine at codon 152 in MAPT might confer a new phosphorylation site, leading to impaired MT binding, disordered retrograde axon transport and an increased risk for primary and secondary tauopathies." (PMID 35392986, 2022). "Furthermore, when three human tauopathy MAPT variants are expressed under the control of the mouse α‐tubulin promoter, in the absence of endogenous Mapt, coiled bodies form inside spinal cord oligodendrocytes, and oligodendrocyte number is reduced by 6 months of age—prior to neuron loss." (PMID 32181929, 2021). "Finally, the various pathogenic MAPT mutations are associated with distinct tauopathies that may be predominately characterized by 3R, 4R, or a mixture of 3R and 4R inclusions." (PMID 34389969, 2021). "Tauopathies, a class of neurodegenerative disorders, are characterized by neurofibrillary tangles (NFTs) in the brain due to pathological aggregation of hyperphosphorylated microtubule‐associated protein tau (MAPT), encoded by the MAPT gene on chromosome 17q21.3." (PMID 32400971, 2020). "Therefore, mechanisms underlying tau aggregation in AD may be different from those involved in tauopathies caused by the MAPT mutations." (PMID 32677986, 2020). "However, although mutations of the MAPT gene have been detected in familial early-onset tauopathies, causative events in the more frequent sporadic late-onset forms and relationships between tau hyperphosphorylation and neurodegeneration remain largely elusive." (PMID 26576216, 2015). "Several clinical studies have shown that florzolotau can bind to 3R, 4R, or mixed 3R and 4R tau isoforms in diverse tauopathies, including AD, PSP, and CBD, as well as FTD due to MAPT mutations." (PMID 40437880, 2025). "The MAPT gene was used to assess its relationship with cognitive function, given its well-established role in tauopathies and early-onset neurodegeneration." (PMID 40725212, 2025).